SCAND1 (SCAN domain containing 1)
Description:
May regulate transcriptional activity.
Synonyms: SDP1; RAZ1
Tractability: PROTAC: ubiquitination databases record sites on it.
Gene: Protein-coding gene on chromosome 20 (35,953,617 to 35,959,472, reverse strand). Ensembl gene ENSG00000171222.
Subcellular location: Nucleus
Subcellular location (Human Protein Atlas): Nuclear speckles
Gene Ontology:
Molecular function: protein binding
Cellular component: nucleus
Genetic constraint (gnomAD): Loss-of-function variants: 6 observed, 3.56 expected, observed/expected ratio (o/e) 1.69, 90% interval 0.81 to 1.95. That is too few expected variants to judge how well the gene tolerates losing a copy. Missense variants: 303 observed, 219.41 expected, observed/expected ratio (o/e) 1.38, 90% interval 1.26 to 1.52. Synonymous variants: 152 observed, 102.94 expected, observed/expected ratio (o/e) 1.48, 90% interval 1.29 to 1.69.
Homologues: Orthologues: chimpanzee SCAND1 (99% identical), macaque SCAND1 (93% identical), pig SCAND1 (79% identical), dog SCAND1 (78% identical), guinea pig SCAND1 (74% identical), rat Scand1 (61% identical), mouse Scand1 (60% identical), Drosophila melanogaster CG12391 (20% identical), Drosophila melanogaster hb (10% identical), Caenorhabditis elegans hbl-1 (9% identical), zebrafish plagl2 (9% identical), Caenorhabditis elegans Y5F2A.4 (7% identical), and 4 more. Paralogues in human: ZNF274 (30% identical), ZNF202 (27% identical), ZKSCAN2 (26% identical), ZNF446 (26% identical), ZSCAN18 (26% identical), ZSCAN1 (25% identical), ZNF174 (25% identical), ZNF496 (25% identical), ZSCAN29 (25% identical), ZSCAN32 (25% identical), ZNF18 (23% identical), ZNF444 (22% identical), and 17 more.
Diseases named in the same sentence as SCAND1 in open-access papers:
SCAND1 is named in the same sentence as 19 diseases in open-access papers, as found by Europe PMC text mining. Sharing a sentence is not in itself a finding about the gene and the disease. The quoted sentences say what the papers report.
prostate carcinoma (5 papers, 2019 to 2023). A carcinoma that arises from epithelial cells of the prostate gland. "The SCAN domain is required for the full transcriptional activity of MZF1, whereas the SCAN-only factor SCAND1 is powerfully associated with chromatin and represses the tumorigenesis of prostate cancer cells." (PMID 31181782, 2019). "High expression of MZF1 correlated with poor prognoses in prostate cancer and kidney cancer, whereas SCAND1 and MZF1 expression correlate with better prognoses in pancreatic cancer and stage III head and neck cancers." (PMID 36982267, 2023). "The anti-EMT and tumor-suppressive effects of SCAND1 overexpression in DU-145 cells are consistent with our previous report showing that SCAND1 overexpression inhibited tumor growth of PC-3 prostate cancer cells in vivo." (PMID 36552758, 2022). "SCAND1 was expressed in normal prostate cells, while its levels were reduced in prostate cancer PC-3 and DU-145 cells, suggesting that SCAND1 expression declines along with prostate oncogenesis." (PMID 36552758, 2022). "Of note, in a mouse tumor xenograft model, SCAND1 overexpression significantly reduced Ki-67(+) and Vimentin(+) tumor cells and inhibited migration and lymph node metastasis of prostate cancer." (PMID 36552758, 2022). "We recently demonstrated that myeloid zinc finger 1 (MZF1) and SCAND1 reciprocally regulated CDC37 gene expression in prostate cancer." (PMID 32204513, 2020). "We found SCAND1 to be expressed in normal prostate cells while its levels were reduced in prostate cancer PC-3 and DU-145 cells, suggesting that SCAND1 expression declines along with prostate oncogenesis." (PMID 31181782, 2019). "Indeed, SCAND1 represses the co-chaperone CDC37 gene (encoding cell division control 37) by interacting with MZF1 and suppressing prostate cancer." (PMID 36982267, 2023). "However, our data indicate that SCAND1 overexpression inhibited migration, lymph node metastasis and tumor growth in prostate cancer cells in vivo." (PMID 36552758, 2022). "We have recently shown that SCAND1 overexpression could inhibit the tumor growth of prostate cancer cells in vivo." (PMID 36552758, 2022). "Indeed, SCAND1 represses the CDC37 gene (encoding cell division control 37) by interacting with MZF1 and suppressing prostate cancer progression." (PMID 36552758, 2022). "SCAND1 was abundantly expressed in normal prostate cells but was reduced in prostate cancer cells, suggesting a potential tumor suppressor role of SCAND1 in prostate cancer." (PMID 31181782, 2019). "To elucidate this possibility, we asked whether tumor initiation by prostate cancer PC-3 cells could be suppressed by SCAND1 expression and by the depletion of MZF1." (PMID 31181782, 2019). "Therefore, our data indicate that while MZF1 positively regulates CDC37, SCAND1 negatively regulates transcription, a finding which could be crucial in mechanisms of prostate cancer progression." (PMID 31181782, 2019). "We found that heat stress induced the expression of SCAND1, SCAND2, and MZF1 bound to HSP90 gene promoter regions in prostate cancer cells." (PMID 36982267, 2023). "High expression of HSP90AA1 correlated with poorer prognoses in several cancer types, although SCAND1 and MZF1 blocked the heat shock responsiveness of HSP90AA1 in prostate cancer cells." (PMID 36982267, 2023). "Consistently, we have shown that overexpressing SCAND1 and MZF1 form oligomers in chromatin and bind to an MZF1-binding site in the promoter region of CDC37 gene, and hetero-oligomers of SCAND1 and MZF1 can repress CDC37 gene expression in prostate cancer." (PMID 36552758, 2022). "In the present study, we showed for the first time that SCAND1 reverses EMT, inhibits tumor cell proliferation, and reduces the invasive capacities of prostate cancer cells." (PMID 36552758, 2022).
prostate carcinoma (continued). "In conclusion, it was demonstrated that pro-oncogenic MZF1 and its potential antagonist SCAND1 coordinately regulate the expression of CDC37, a factor that is essential for prostate cancer tumorigenesis." (PMID 31181782, 2019). "We analyzed co-expression correlations of MZF1, SCAND1, and SCAND2 genes in prostate cancer." (PMID 36982267, 2023). "We next examined whether the gene expression of SCAN-TFs (MZF1, SCAND1, and SCAND2(P)) was correlated with HSF1 or HSF4 gene expression in prostate cancer specimens derived from patients." (PMID 36982267, 2023). "Nevertheless, the current analyses could not find any prognostic value of SCAND1 expression in clinical prostate cancer." (PMID 36552758, 2022). "To clarify the prognostic values of MZF1 and SCAND1, we next investigated whether MZF1 and SCAND1 high or low expression correlated with survival rates of patients suffering from pancreatic, head and neck, kidney, and prostate cancers." (PMID 36552758, 2022).
head and neck cancer (2 papers, 2022 to 2023). A primary or metastatic malignant neoplasm affecting the head and neck. "MZF1 and SCAND1 high expression correlated with better prognoses in patients suffering from pancreatic cancer and head and neck cancers, suggesting that elevated SCAND1-MZF1 co-expression could inhibit EMT and invasive phenotypes in cancer." (PMID 36552758, 2022). "We showed that high expression of SCAN-TFs (SCAND1, SCAND2, and MZF1) were predictive biomarkers of enhanced prognoses for patients suffering from pancreatic cancer and head and neck cancers." (PMID 36982267, 2023). "Of note, high RNA expression of SCAND2, SCAND1, and MZF1 correlated with enhanced prognoses of pancreatic cancer and head and neck cancers." (PMID 36982267, 2023). "Kaplan–Meier analysis showed high expression of SCAND1 and MZF1 to correlate with better prognoses in pancreatic cancer and head and neck cancers, although with poorer prognosis in kidney cancer." (PMID 36552758, 2022).
prostate adenocarcinoma (2 papers, 2022 to 2023). "HSP90AA1 gene expression was negatively correlated with the gene expression of MZF1(ZSCAN6), SCAND1, SCAND2, and HSF4 in prostate adenocarcinoma specimens." (PMID 36982267, 2023). "In prostate adenocarcinoma specimens, the expression of MZF1 was positively correlated with both SCAND1 and SCAND2 RNA expression." (PMID 36982267, 2023). "Consistent with this, gene expression of SCAND2, SCAND1, and MZF1 was negatively correlated with HSP90 gene expression in prostate adenocarcinoma." (PMID 36982267, 2023). "Consistently, the co-expression analysis in TCGA PanCancer Atlas revealed that SCAND1 and MZF1 expression was negatively correlated with EMT driver genes, including CTNNB1, ZEB1, ZEB2 and TGFBRs, in prostate adenocarcinoma specimens." (PMID 36552758, 2022). "We showed that SCAND1 and MZF1 are mutually inducible, localized in heterochromatin with HP1γ, spatially co-localized in cancer cells in vitro, and coordinately expressed in many cases of clinical prostate adenocarcinomas." (PMID 36552758, 2022). "Next, we examined whether SCAND1 and MZF1 expression levels were correlated in clinical prostate adenocarcinoma specimens." (PMID 36552758, 2022). "Indeed, SCAND1 and MZF1 expression was significantly correlated in prostate adenocarcinomas, indicating that these SCAN domain proteins are consistently co-expressed." (PMID 36552758, 2022).
anxiety disorder (1 paper, 2021). A category of psychiatric disorders which are characterized by anxious feelings or fear often accompanied by physical symptoms associated with anxiety. "Scand1 is suggested to be a potential druggable target in the treatment of anxiety disorder." (PMID 34707778, 2021).
kidney cancer (1 paper, 2022). Primary or metastatic malignant neoplasm involving the kidney. "On the other hand, SCAND1 and MZF1 high expression correlated with poor prognosis in patients suffering from kidney cancer." (PMID 36552758, 2022).
pancreatic ductal adenocarcinoma (1 paper, 2023). An infiltrating adenocarcinoma that arises from the epithelial cells of the pancreas. "High expression levels of SCAND1, SCAND2 and MZF1 genes were significantly correlated with enhanced prognosis of patients suffering from pancreatic ductal adenocarcinoma (DAC)." (PMID 36982267, 2023).
prostate tumor (1 paper, 2022). "Next, we examined whether SCAND1 overexpression in prostate tumors could alter pelvic lymph node metastasis in the mouse xenograft model." (PMID 36552758, 2022). "Regarding EMT drivers, both SCAND1 and MZF1 expression negatively correlated with CTNNB1 expression in prostate tumor specimens." (PMID 36552758, 2022).
tumor (4 papers, 2019 to 2023). "We found that SCAND1 expression correlated with maintaining epithelial features, whereas the loss of SCAND1 was associated with mesenchymal phenotypes of tumor cells." (PMID 36552758, 2022). "Ki-67 expression, a marker of proliferating tumor cells, was significantly suppressed by SCAND1 overexpression in in vivo tumors." (PMID 36552758, 2022). "Enhanced co-expression of E-cadherin was seen in/around the cells overexpressing SCAND1, indicating that SCAND1 influenced the tumor cells towards an epithelial phenotype." (PMID 36552758, 2022). "Our findings provide insight into how MZF1-driven CDC37 expression promotes cancer progression and how SCAND1 functions as a potential tumor suppressor by repressing CDC37." (PMID 31181782, 2019). "We next used a mouse tumor xenograft model to examine whether SCAND1 could inhibit tumor cell EMT, migration, and metastasis." (PMID 36552758, 2022). "In addition, SCAND1 overexpression suppressed tumor cell proliferation by reducing the MAP3K-MEK-ERK signaling pathway." (PMID 36552758, 2022). "These suggest that MZF1 alone is oncogenic, whereas repressing complexes of SCAND1 and MZF1 is tumor suppressor, depending on their gene expression in cancer cases." (PMID 36982267, 2023). "Both SCAND1 and MZF1 overexpression significantly inhibited tumor cell proliferation, while SCAND1 overexpression more significantly inhibited it." (PMID 36552758, 2022). "Further, the expression of NDUFB7, AURKAIP1, ROMO1, SCAND1, GADD45GIP1, and NDUFA13 was upregulated in the four tumor subtypes compared with normal adjacent tissue." (PMID 34996995, 2022). "Our data indicate that elevated expression of SCAND1 and MZF1 can reverse the hybrid EMT status of tumor cells to a more epithelial status, although vimentin and nuclear β-catenin remained, suggesting that the cells were not fully epithelial." (PMID 36552758, 2022). "Moreover, SCAND1 and MZF1 are mutually inducible and form oligomers that can reverse epithelial-to-mesenchymal transition (EMT), tumor growth, and migration by repressing EMT driver genes and mitogenic protein kinase (MAPK) genes." (PMID 36982267, 2023). "Moreover, the overexpression of SCAND1 inhibited the phosphorylation of ERK-1/2 and tumor cell proliferation." (PMID 36552758, 2022). "We examined whether SCAND1 and MZF1 could alter tumor cell proliferation and EMT." (PMID 36552758, 2022).
cancer (3 papers, 2019 to 2023). A tumor composed of atypical neoplastic, often pleomorphic cells that invade other tissues. "Here, we investigate the involvement of SCAND1 in reversing EMT in cancer." (PMID 36552758, 2022). "Our data also touch upon the prognostic importance of SCAND1 and MZF1 expression in evaluating several types of cancer." (PMID 36552758, 2022). "Nevertheless, it will be important to determine how nuclear E-cadherin and SCAND1 regulate EMT and cancer stem cells." (PMID 36552758, 2022). "We next hypothesized that the repressive transcription factors SCAND1, SCAND2 and MZF1(ZSCAN6) would contribute to enhanced prognosis in cancer patients, whereas high expression of HSP90 genes would likely be involved in a poorer prognosis." (PMID 36982267, 2023). "Our data suggest that SCAND1 and MZF1 might also regulate molecular chaperone expression and the cell stress response in cancer." (PMID 36552758, 2022). "Our data also suggest that SCAND1 could suppress the WNT/β-catenin signal, which is crucial for EMT and cancer stemness." (PMID 36552758, 2022). "Furthermore, we have tested the hypothesis that the relationship between MZF1 and SCAND1 regulates CDC37 expression and thereby cancer growth." (PMID 31181782, 2019).
SCAND1 also shares sentences with these, for which no sentence is quoted: pancreatic cancer (2 papers); Anxiety (1); cervical cancer (1); colorectal cancer (1); head and neck squamous cell carcinoma (1); ischemic stroke (1); lung adenocarcinoma (1); Lymph-Node Metastasis (1); meningioma (1); sarcoma (1).